EGFR (epidermal growth factor receptor)
Diseases named in the same sentence as EGFR in open-access papers (continued):
Sharing a sentence is not in itself a finding about the gene and the disease.
cancer (continued). "For example, eight patients across four cancer types were identified with low expression of EGFR when receiving cetuximab or lapatinib, or of ERBB2 when receiving erlotinib." (PMID 29783934, 2018). "In this case, although, the direct role of Fas in EGFR signaling was not demonstrated, its presence was reported essential for the cancer-promoting activities of other parallel pathways that made the EGFR activity redundant." (PMID 30127519, 2018). "Cytotoxicity and NPs cellular uptake was analyzed with MDA-MB-468 type cancer cells and the EGFR expression was confirmed by PCR, qualitatively and quantitatively." (PMID 30408068, 2018). "Targeting mitotic cells is feasible for EGFR-overexpressing cancer cells, as these cells intrinsically undergo more cell proliferation." (PMID 30544639, 2018). "Epidermal growth factor receptors (EGFR) are an important class of kinase enzymes used in cancer treatment, which are overexpressed in several tumours, such as brain, liver, colon, prostate, breast, and non-small-cell lung cancers." (PMID 29251017, 2018). "We found that EGFR tyrosine kinase inhibitors and the monoclonal humanized anti-EGFR antibody Cetuximab, which are drugs approved for the treatment of several types of cancers, increased the constitutive expression of HBD1 in vitro and ex vivo." (PMID 30575780, 2018). "Despite the early promise of EGFR-inhibition in the treatment of cancer, the development of resistance to treatment is observed in the majority of patients." (PMID 30054711, 2018). "In this case, cells overexpress EGFR and its strong signalling promotes cancer cell survival, in spite of trastuzumab binding to HER2 remaining unchanged." (PMID 30388834, 2018). "The unique property of mitotic EGFR endocytosis offers an important opportunity for developing cancer therapy that targets both EGFR and mitosis." (PMID 30544639, 2018). "The synergistic effect between TGF‐β and EGFR on promoting cancer progression has also been confirmed in several cancer types." (PMID 29215776, 2018). "It remains elusive why a SPINK1-specific mAb can be more effective than an EGFR-oriented mAb in reducing cancer malignancy." (PMID 30333494, 2018). "Next, we explored the effects of intramolecular changes on the KD of EGFR dimerization utilizing two EGFR mutants frequently found in various cancers, EGFRvIII and EGFR L858R." (PMID 30543635, 2018). "EGFR signaling axis is deregulated in various solid tumors, including prostate cancer, being commonly upregulated and fostering cancer cell growth." (PMID 29415999, 2018). "Like other receptor tyrosine kinases, EGFR contributes to cancer progression through effects on cell proliferation, metastasis, angiogenesis, and inhibition of apoptosis." (PMID 29933620, 2018). "The authors also reported that the loss of Smurf2 destabilizes EGFR, and reduces the clonogenic survival of EGFR-expressing cancer cell strains." (PMID 30116722, 2018). "Insight into the effect of DHA on cancer cells can be gained through determination of its impact on EGFR localization within the membrane lipid rafts." (PMID 30400136, 2018). "The adhesion of cancer cells to fibronectin triggered activation of protein tyrosine kinase and intervention with tyrphostin-25, a competitive EGFR tyrosine kinase inhibitor abolished the effect." (PMID 29455663, 2018). "The goal of the present study was to investigate the influence of ST6Gal-I on another important receptor that controls cancer cell behavior, EGFR." (PMID 29402301, 2018). "The expression of epidermal growth factor receptor (EGFR) has been identified as key molecule in several human cancers, including mCRC." (PMID 30427914, 2018). "Targeting those proteins led to the development of cancer therapeutics such as erlotinib and gefitinib (EGFR inhibitors), LY294002 (PI3K inhibitor), peritosine (Akt inhibitor), rapamycin and sirolimus (mTOR inhibitors), and many others." (PMID 29713280, 2018).
cancer (continued). "The monoclonal antibodies cetuximab and panitumumab were developed to target EGFR on the surface of cancer cells." (PMID 29254887, 2018). "IGF1R as well as EGFR signaling pathway plays a critical role in cancer cell survival, facilitating resistance to γ-radiation and anticancer drugs." (PMID 30013043, 2018). "Strikingly, SPINK1 reprograms the expression profile of cancer cells, causing prominent epithelial-endothelial transition (EET), a phenotypic switch mediated by EGFR signaling but hitherto rarely reported for a SASP factor." (PMID 30333494, 2018). "The tyrosine kinase activity of EGFR has been a major therapeutic target for cancer; however, the efficacy of EGFR tyrosine kinase inhibitors to treat cancers has been challenged by innate and acquired resistance at the clinic." (PMID 29358623, 2018). "Inhibition of EGFR signaling using erlotinib considerably reduces the cancer stemness and reverses the endocrine resistance by inducing the expression of ER." (PMID 29455658, 2018). "The main biologically active component of green tea, epigallocatechin gallate (EGCG), inhibits the EGFR activation and its downstream signaling pathways in several human cancer cell lines." (PMID 30518103, 2018). "In a study using the TLR8 agonist with an anti-EGFR monoclonal antibody (cetuximab), an increase in NK cell-mediated cancer cell lysis and an enhancement of DC cross-priming of EGFR-specific CD8+ T cells were observed." (PMID 29854832, 2018). "Though EGFR expression has been supported to growth and metastatic stages of cancer, its effects on survival is still a debate." (PMID 30643798, 2018). "We performed one injection of the can225-IR700 with two exposures of NIR light in order to perform a proof-of-principle study for demonstrating that NIR-PIT with can225-IR700 was effective to treat EGFR-expressing canine cancer models." (PMID 29721181, 2018). "Genetic deletion or pharmacological inhibition of EGFR resulted in reduced OS formation and progression in mouse models of OS by inhibiting the proliferation and survival of cancer‐initiating osteoblastic cells." (PMID 30361264, 2018). "Recently, there is increased appreciation of reverse E-cadherin/catenin–EGFR cross-talk as part of a bidirectional signaling axis in cancer pathogenesis." (PMID 29468433, 2018). "Since then, there has been little progress in understanding the influence of Fas signaling on the EGFR pathway in cancer." (PMID 30127519, 2018). "We further modeled two cell membrane proteins, epidermal growth factor receptor (EGFR), and E-cad, because these proteins are heavily decorated with N-glycans and involved in cancers as a result of aberrant or excessive glycosylation." (PMID 29541627, 2018). "Long-term knockdown of EGFR indeed decreased GBM cell viability at day 7 because EGFR was an oncoprotein for cancer cell proliferation." (PMID 30016965, 2018). "Since these mutations significantly affect the effectiveness of targeted medicine, EGFR analysis is becoming more and more a routine test before selecting targeted therapy for related cancers, such as NSCLC." (PMID 30393665, 2018). "The present results suggest that EGFR is stabilized in cancer cells that overexpress GGA2, likely supporting growth of HCC and CRC." (PMID 29358589, 2018). "Thereinto, EGFR is a paradigm and its intracellular signaling pathways are relevant to the emergence and progression of various cancers, especially NSCLC." (PMID 29455669, 2018). "It was revealed that the administration of elemene or gefitinib, at concentrations of 40 μg/ml or 5 μM, respectively, only exerted mild effects on cellular viability in both A549 and H1299 cells, the two cancer cell lines proved to be EGFR-TKI resistant." (PMID 30555330, 2018). "Better understanding of PHLDA2′s regulation and its interactions with membrane PIPs/inhibition of AKT activation can yield novel therapeutic options for the treatment of patients with EGFR/ErbB2-driven cancers." (PMID 29861842, 2018).
cancer (continued). "Overexpression of EGFR, sometimes accompanied by gene amplification, is observed in a wide variety of cancers including gastrointestinal cancers." (PMID 29989003, 2018). "EGFR is important in progression of many cancer types; thus, it became one of the major targets in cancer following the development of several targeting agents." (PMID 30445726, 2018). "We found that STAT3 activation (phosphorylation) and LGR5 mRNA levels were individually induced by EGF, revealing that EGFR is capable of exacerbating cancer stemness properties; this finding is consistent with that of a previous study." (PMID 30068339, 2018). "Next, a multiplexed assay platform was established for the anti-cancer drug and EGFR inhibitor gefitinib." (PMID 29895862, 2018). "Src kinase directly phosphorylates EGFR at Tyr 845 and promotes cell adhesion, motility, and cancer development." (PMID 29867020, 2018). "In cancer cells, PKM2 translocates to the nucleus from the cytoplasm in response to the epidermal growth factor receptor (EGFR) signaling, and is associated with a higher incidence of distant metastases." (PMID 30333907, 2018). "EGFR migration signaling in cancer cells has been extensively investigated, and several pathways, such as cell adhesion, Src, Akt, MAPK and endosomal signaling pathways, have been identified." (PMID 29455656, 2018). "The MAPK and PI3K/Akt pathways are downstream of the EGFR and are important for EGFR mediated proliferation and cancer cellular survival, respectively." (PMID 30008698, 2018). "We investigated different anti-EGFR antibodies and levels of EGFR expression of cancer cells on capture performance in order to establish capture conditions for clinical applications." (PMID 30104638, 2018). "The localization of nuclear EGFR, which has been detected in various cancers in the last decade, functions as a transcription factor for cell proliferation, angiogenesis and resistance to standard therapy." (PMID 29950164, 2018). "In another example, the ectodomain shedding of epidermal growth factor receptor (EGFR) ligands, involved with the pathogenesis of hyper-proliferative disorder, such as cancer, has been shown to be contributed by ADAM-9, -10, -12 and -17." (PMID 29393911, 2018). "These researchers binding gold nanoparticles to an antibody EGFR (with anti EFGR) have been able to attach mentioned nanoparticles to cancer cells and cause specific destruction of cancer cells with gold nanoparticles." (PMID 34466436, 2018). "EGFR and EpCAM were expressed in suprabasal layers of normal mucosa and were strongly expressed in primary carcinomas, with a frequent coexpression at the single-cell level." (PMID 30261040, 2018). "Meanwhile, HIF-1α is frequently induced through EGFR activation and mediates carcinoma angiogenesis as well as promotes EMT and metastasis." (PMID 29499765, 2018). "CUP adenocarcinomas and poorly differentiated carcinomas harboured the highest frequency of variants in genes involved in signal transduction pathways (e.g. MET, EGFR, HRAS, KRAS, and BRAF)." (PMID 29973234, 2018). "EGFR activation is frequently induced to mediate carcinoma invasion and metastasis through promoting EMT." (PMID 29499765, 2018). "For arming the modular UniCAR platform, we established a novel bivalent TM for redirection of UniCAR T cells against EGFR+ carcinoma cells." (PMID 29876011, 2018). "The development and introduction of monoclonal antibodies targeting EGFR and angiogenic pathways have expanded treatment options for cancer patients." (PMID 28744667, 2017). "Inhibition of epidermal growth factor receptor (EGFR) signaling has been suggested as a therapeutic strategy for several types of cancer with high mortality rates, including non-small cell lung cancer (NSCLC)." (PMID 27935858, 2017).
cancer (continued). "This offers a potential strategy for developing NP-based TRT for the treatment of EGFR-positive cancer." (PMID 29071190, 2017). "Although the EGFR-Ras-Raf-MEK-ERK signaling network has been identified as a novel target-based approach for cancer treatment, it is still unclear if the signal pathway is related with FOXD3." (PMID 27926503, 2017). "Here we demonstrated a correlation between EGFR mutation and YAP1 expression using both human tissues and cancer cell lines." (PMID 29163769, 2017). "Lnc-EGFR links an immunosuppressive state to cancer by promoting Treg cell differentiation, thus offering a potential therapeutic target for HCC." (PMID 28541302, 2017). "A recombinant immunotoxin comprising TGFα and a modified Pseudomonas exotoxin A (PE38) derived from Pseudomonas aeruginosa was developed for treatment of EGFR-expressing malignant tumors, e.g. brain tumors." (PMID 28473665, 2017). "Taken together, we suggest that the EGF-conjugated GNP complex coupled with NTP treatment efficiently targets EGFR-expressing cancer cells." (PMID 28887524, 2017). "The epidermal growth factor receptor (EGFR), which considered as a signal of poor prognosis, overexpressed in approximately 30% of solid tumors during cancer therapy." (PMID 28261093, 2017). "Further clinical studies are needed to prove the therapeutic effects of CMP in cancer patients, particularly in whom EGFR and IL-17RA play a pivotal role." (PMID 29212184, 2017). "Combinations of EGFR-targeting therapies with immunomodulatory approaches and cancer vaccines constitute a promising way to increase their clinical effectiveness." (PMID 29056908, 2017). "To elucidate this, we examined the expression of c-MET and EGFR levels in NRF2-silenced cancer cells." (PMID 29291022, 2017). "In one example, ctDNA was isolated from serial plasma samples taken from NSCLC patients on a clinical trial for a third generation EGFR inhibitor and analyzed with a targeted cancer personalized profiling by deep sequencing (CAPP-Seq) panel." (PMID 28431544, 2017). "Overexpression of EGFR in cancer is partly due to gene amplification, but the underlying mechanisms are not yet fully elucidated." (PMID 29261144, 2017). "We have previously synthesised epidermal growth factor (EGF)-tagged gold (Au) NP (i.e. 111In-EGF-Au) which were designed for the molecular radiotherapy of EGF receptor (EGFR)-positive cancer." (PMID 29071190, 2017). "Cetuximab, a monoclonal antibody that binds to the epidermal growth factor receptor, has been introduced as an antitumor therapy; however, secondary resistance and side effects significantly limit its effective use in these cancers." (PMID 28800074, 2017). "A pilot PET experiment using 68Ga-cetuximab as transurethrally administered radiotracer revealed functional expression of epidermal growth factor receptor as representative molecular characteristic of engrafted cancer cells in the bladder." (PMID 29169339, 2017). "Aberrant activation of EGFR in human cancer typically occurs through alterations in the EGFR gene, but can also be the result of defects in physiologic EGFR feedback regulation." (PMID 29229958, 2017). "As a typical cell membrane receptor, epidermal growth factor receptor (EGFR) is highly expressed in various types of cancer and identified as an oncogenic driver as well as a validated target for cancer therapy." (PMID 28724430, 2017). "Research has indicated that GPCR transactivation of epidermal growth factor receptor (EGFR) is significantly involved in cancer cell proliferation." (PMID 29262666, 2017). "To this end we developed cancer models for functional dissection of resistance to anti-EGFR therapy in vitro and in vivo." (PMID 28507280, 2017). "We repeated the assay with mRFP-labeled cells of a different cancer cell line, HCC827 which also harbors an EGFR mutation (exon 19 deletion)." (PMID 28429795, 2017).
cancer (continued). "In this study, GE11 peptide-conjugated Se NPs (GE11-Se NPs), a nanosystem targeting EGFR over-expressed cancer cells, were synthesized for oridonin delivery to achieve enhanced anticancer efficacy." (PMID 29019267, 2017). "The mAb806 binds to an epitope exposed only in the transitional untethered form of EGFR when it is overexpressed in cancer." (PMID 28752098, 2017). "The authors showed that the EGFR level on the surface of cancer cells remains constant after treatment with GE11 polyplexes, indicating an EGFR recycling process with a prolonged receptivity of the cells for circulating GE11 polyplexes." (PMID 29271876, 2017). "For example, the EGFR mutation and CDK1-mediated kinase activities contribute to USP24 downregulation, resulting in cancer formation by affecting its substrates." (PMID 27991932, 2017). "Recent evidence has shown that miR-223 serves as an onco-miRNA during development of chemotherapy resistance and cancer metastasis; however, its role in resistance to EGFR-TKIs remains controversial." (PMID 28507201, 2017). "EGFR, a member of the receptor tyrosine kinase family, plays a pivotal role in several cellular functions and is considered an attractive target for cancer therapy." (PMID 28698660, 2017). "It is therefore intriguing to have found that the EGFR pathway promotes the cancer stem-like phenotype in IBC in the current study." (PMID 28978083, 2017). "EGFR overexpression and mutation and loss of PTEN function are frequently observed in human cancers." (PMID 29038421, 2017). "Enhanced EGFR levels have been correlated with poor prognosis in various cancers including head and neck, bladder, ovarian, cervical, and esophageal cancers." (PMID 28574446, 2017). "Given the function of EGFR in diverse cellular processes, two therapeutic approaches, i.e., TKIs and mAbs, are currently employed for targeting EGFR in various human cancers." (PMID 29140271, 2017). "CD16+ and/or CD56+ cells are considered the main effectors of the ADCC triggered by the cetuximab against cancer cells overexpressing EGFR." (PMID 29354119, 2017). "In several cancers, the amount of EGFR with nuclear localization was increased, indicating its ability to promote cancer cells to survive." (PMID 28338617, 2017). "Another function of the tyrosine kinase-independent EGFR is to protect cancer cells from autophagic cell death induced by glucose starvation, when EGFR interacts and stabilizes the sodium/glucose cotransporter 1 (SGLT1) to maintain intracellular glucose level." (PMID 28338617, 2017). "Over the decades, many bacterial‐ and plant‐based targeted toxins have been developed with the goal of targeting cancers reliant upon EGFR overexpression." (PMID 28755527, 2017). "Intriguingly, EGFR is also proved to regulate cancer metabolism by the finding that it keeps the intracellular level of glucose through maintaining the protein stability of sodium/glucose cotransporter 1 (SGLT1) in a kinase activity independent manner." (PMID 28724430, 2017). "In conclusion, both signaling pathways, MAPK and PI3K/AKT, acting downstream of oncogenic RAS confer resistance of cancer cells to anti-EGFR antibody therapy in vitro and in vivo." (PMID 28507280, 2017). "KIAA1199 promotes cancer cell survival through EGFR signaling and through promoting glycogen breakdown and preventing apoptosis." (PMID 28179576, 2017). "For example, mutations leading to the overexpression of epidermal growth factor receptor (EGFR) are present in a number of cancer cells and are thought to contribute to the malignant phenotype." (PMID 29016600, 2017). "In their work, EGFR activation stimulates de novo lipogenesis with consequent accumulation of LDs expressing increased levels of PLIN2 protein in various CR cancer cells." (PMID 28883835, 2017). "In the IC50 maps grouped by anti-cancer Fv, the LH-diabodies with anti-EGFR DL11 or 11F8 domains had very high cytotoxicity, with little dependency on the kind of anti-CD3 fragments used." (PMID 28588218, 2017).